IL5 (interleukin 5)
Diseases named in the same sentence as IL5 in open-access papers (continued):
Sharing a sentence is not in itself a finding about the gene and the disease.
infection (continued). "Lange and colleagues used a similar approach to immunize mice with Onchocerca volvulus L3 and also observed fast protection, which led to reduction of the recovery rates by 54% to 77% between five and 28 days post challenge infection (p.i.), and this was also associated with eosinophils and IL-5." (PMID 22413031, 2012). "PCA 2 was made up of the cytokines IL-4 and IL-5 (Th2 cytokines) as well as some antibodies (anti-cercariae/IgM and IgG2 and anti-egg IgM previously associated with both exposure to and protection against infection)." (PMID 21039611, 2010). "This analysis showed a clear difference in levels of parasite-specific antibodies and levels of the Th2 cytokines (IL-4 and IL-5), both of which were significantly higher in older egg-negative people suggesting that these were associated with resistance to infection/re-infection." (PMID 21039611, 2010). "In addition to low eosinophil numbers, IL‐5–deficient mice have significantly less B‐cell accumulation and IgM production at the site of infection, which might further support a role for IgM as an anti‐worm effector." (PMID 32145033, 2020). "In addition, in animals inoculated with P. brasiliensis alone and those coinfected, sustained production of Th1 cytokines (i.e., IL-2 and IL-5) in both phases of infection can also indicate a protective response associated with the resistance of infected hosts against disease progression." (PMID 31019973, 2019). "Therefore, IL-4R−/−/IL-5−/− signalling may also be essential for the control of infections with human pathogenic filariae." (PMID 31109364, 2019). "Therefore, measurement of Th2 cytokines in response to mitogen stimulation, in particular, IL5 could potentially be a useful predictive marker of future risk for infection in patients with MM especially during maintenance therapy." (PMID 29051761, 2017). "In addition, high IL-13 and IL-5 expression could also be used to detect patients at risk of developing acute exacerbations of infection." (PMID 28680858, 2017). "The IL-5 produced is positively associated with increased downstream eosinophil number and increases in specific IgE levels, implicating this cytokine boost and its down-stream consequences in the production and maintenance of IgE, and subsequent re-infection immunity." (PMID 23556029, 2013). "Here we investigate if praziquantel treatment of human schistosomiasis haematobium also boosts circulating IL-5, the immunological and parasitological factors that predispose to this, and the relationship between these and subsequent immunity to post-treatment re-infection." (PMID 23556029, 2013). "In mouse models, high levels of IL-6, IL-5, IL-8, and granulocyte-macrophage colony-stimulating factor (GM-CSF) are predictive of ensuing infection." (PMID 41503525, 2026). "Concentrations of Th-2 cytokines (IL-4, IL-5, and IL-13) as well as expression all the genes (IL-4, IL-5, and IL-13) were found to be greater (p < 0.05) in resistant sheep on different days post infection." (PMID 41993907, 2026). "In severe infection, mRNAs of IL‐4, IL‐5, IL‐6, IL‐10 and IL‐13 highly expressed compared to the non‐infected control, but the interferon‐ (INF)‐γ expression remained unaltered." (PMID 41503693, 2026). "High-dose infection with all the strains elicited significant increases in GM-CSF, IL-1β, IL-2, IL-4, IL-5, IL-6, and IL-12p70 when compared with the PBS control." (PMID 40333117, 2025). "The median pre-infection biomarker level was higher in each instance, and this difference was significant for IL-6 (p = 0.0088) and trending for IL-21, IL-5 and fractalkine (p = 0.0192, 0.0503 and 0.0533 respectively)." (PMID 40862133, 2025). "In subtype C, we found that the changes in the biomarker profiles post infection compared to pre-infection were due to increases in TNFα, IL-10, IL-6, IL-13, IL-5, IFNγ, IL-12, IL-4, ITAC, IL-17α, and IL-23." (PMID 40862133, 2025).
infection (continued). "Ornithonyssus bacoti mites were fed on untreated and DR-treated microfilaremic Il4rα-/-/Il5-/- mice at 70 days post-infection (dpi)." (PMID 40644522, 2025). "Overexpressed in keratinocytes of AD patients, IL-33 is rapidly released in response to injury or infection, triggering Th2 polarization by activating immune cells such as mast cells and group 2 innate lymphoid cells (ILC2s) to produce IL-4, IL-5, and IL-13." (PMID 41020006, 2025). "The concentration of chemokines CxCL1/KC/GRO-α, CxCL2/MIP-2, CCL5/RANTES and cytokines TNF-α, IL-1β, IFN-γ, IL-5, IL-6, IL-9, IL-10, IL-13, IL-17, IL-23 circulating in blood were measured in experimental animals on day 15 post-infection." (PMID 40445994, 2025). "Here we show that colonic lamina propria ILC2s expand in response to CR infection and secrete IL-4, IL-5 and IL- 13, which are involved in maintenance of the intestinal barrier function, tissue repair and mucus secretion." (PMID 40591723, 2025). "Beyond IFN-γ as a differential proinflammatory cytokine in TB, cytokines such as IL-5, and IP-10 show potential as biomarkers to discriminate infection status in high-burden TB settings." (PMID 41471181, 2025). "Initial negative stool microscopy results highlight the necessity of repeated testing or serological methods (e.g., sensitive biomarkers like IL-5) for early infection detection." (PMID 41488892, 2025). "Whilst initial infection stimulates a mixed Th1/Th2 cytokine response, parasite egg production from 4-5 weeks post-infection promotes a dominant type 2 inflammatory response with high levels of IL-4, IL-5 and IL-13 (weeks 6–8)." (PMID 41296814, 2025). "This response is characterized by the production of cytokines such as IL-4, IL-5, IL-6, IL-10, and IL-13, which deactivate infected macrophages and allow parasite dissemination at infection sites and internal organs." (PMID 40391226, 2025). "A Zimbabwean study assessing the cytokine response to AWA stimulation of PBMCs revealed that IL-10 was most strongly correlated with Sh infection intensity, and that participants with high intensity infection also tended to produce lower IL-5 levels." (PMID 39250522, 2024). "Conversely, IL-5, IL-6, and IL-12 (P40) experienced a notable decrease on day 4 post-infection, suggesting a distinct regulatory role of c-FLIP in macrophages compared in vivo." (PMID 39038037, 2024). "L. brevis 23017 improved SIgA levels by regulating the level of IL-5, IL-13, pIgR, J-chain and IgA α-chain to enhance the immune function against S. typhimurium C7731 infection." (PMID 38930517, 2024). "All cultures accumulated the pro-inflammatory cytokines MCP-1 and VEGF-A during the 48 hr post-infection period; however, there was only a trend for an increase of IL-5 (p = 0.061) in Week 2 SIV-infected cultures relative to pre-SIV at 24 hr." (PMID 39229223, 2024). "T helper 2 cells can produce cytokines, including IL-4, IL-5, IL-10, and IL-3,27 and the response of these cells plays a central role in protection against infection." (PMID 39807418, 2024). "Infection with helminths induces polarized type 2 immunity characterized by elevated expression of cytokines, including IL-4, IL-5, IL-10, and IL-13." (PMID 38166140, 2024). "At 72 h post‐infection, these cytokine/chemokine levels shifted with significantly lower IFNγ and IL‐4, significantly higher IL‐5, IL‐10, IL‐17a, and CCL‐5/RANTES, and comparable IL‐2 and TNFα levels." (PMID 37990641, 2024). "On day 6 of infection, the study found elevated IL-4, IL-5, IL-13, and IL-10 levels in infected mice." (PMID 38166140, 2024). "Although the fungal burden in the lung tissue was not significantly different among the groups, the levels of IL-4 and IL-5 were strikingly increased in the LincR-PPP2R5C KO mice at 14 days post infection." (PMID 39287443, 2024).
infection (continued). "This immune response initially predominates as Th1 inflammatory responses (e.g., TNF-α, IFN-γ, IL-12) during the infection’s initial phase, but as the disease progresses, it shifts to a permissive Th2 response (IL-4, IL-5, IL-13)." (PMID 39093864, 2024). "Even prior to infection, ILC2s in all tissues constitutively secrete IL-5, which sustains homeostatic eosinophil production in the bone marrow." (PMID 38277692, 2024). "During infection, IL-13 induces eotaxin production, thereby recruiting eosinophils into the tissue, where they are maintained by locally produced IL-5 and secrete factors that contribute to type 2 inflammation." (PMID 38277692, 2024). "Cytokines are pivotal mediators of immune responses, and the host can stimulate the production of Th1 and Th2 cytokines, such as IL-4, IL-5, IL-6, IL-10, and IL-13, to combat infections." (PMID 38786064, 2024). "Expression of IL-5 was driven by interactions between EcoHIV infection and B/F/TAF treatment [interaction: F = 4.080, p = 0.0497; no main effect of EcoHIV: F = 3.500, p = 0.0682; no main effect of B/F/TAF: F = 1.202, p = 0.2791]." (PMID 38786105, 2024). "In contrast, IL-1α was decreased at day 4 after infection, whereas IL-5, CCL3, CCL4 (MIP-1β), and IFN-γ were significantly reduced in IkkαLyve-1 BALF at day 7 after infection." (PMID 39007717, 2024). "During the time course of infection, the Th1 immune response alters to a Th2 response, with increased levels of IL-4, IL-5, and IL-13." (PMID 39329761, 2024). "While we did not detect vaccination-associated differences in plasma levels for IL-5, IL-23, IL-33, and CCL2/MCP-1, we observed a step-wise reduction of IL-18 levels after post-infection vaccinations in individuals with ongoing PCC." (PMID 38316833, 2024). "Selective ablation of TSLP in dermis-resident macrophages reduces the numbers of IL-5+ type 2 innate lymphoid cells, eosinophils and dermis-resident macrophages, and ameliorates infection." (PMID 38030609, 2023). "Clustering identified a group of inflammation-related cytokines secreted on the apical side in response to infection, including IL-5, IL-17, IL-10 and IL-1RA." (PMID 37822359, 2023). "Here, we show that thymic stromal lymphopoietin (TSLP) and IL-5+ type 2 innate lymphoid cells are also required to maintain dermis-resident macrophages and promote infection." (PMID 38030609, 2023). "Both TSLP signaling and IL-5+ innate lymphoid cell 2 (ILC2s) were shown to maintain the number of dermal TRMs and promote infection." (PMID 37066418, 2023). "It is noteworthy that high paramyosin levels correlate with high IL-5 levels during the second week of infection." (PMID 37242348, 2023). "In the experiments against N. brasiliensis, it has been shown that, after 5 days of infection, the IL-25 activated iILC2s to highly express IL-13, IL-5 and IL-4, and only the iILC2s expressed the Th2 cytokines." (PMID 37173731, 2023). "In contrast, we show that ILC2s produce IL-5 both at homeostasis and during F. tularensis LVS infection, and that neutralization of IL-5 leads to enhanced bacterial burdens following infection." (PMID 36602520, 2023). "Our findings revealed that inflammatory cytokines, including TNF-α and IL-6, Th1-related cytokine IFN-γ, and Th2-related cytokine IL-5 were significantly elevated in HD patients after breakthrough infection compared to after booster immunization." (PMID 37515030, 2023). "A potential role for ILC2s and IL-5 during F. tularensis LVS infection is in line with a recent study suggesting their importance in regulation of IgM production by B cells in responses to F. tularensis LVS–derived LPS vaccination in murine models." (PMID 36602520, 2023). "After infection by worms, IL-5 can enhance eosinophil activation and kill larvae at the site of infection by releasing toxic eosinophil granules." (PMID 37501169, 2023).
infection (continued). "Intriguingly, after 30 days of infection, the levels of all cytokines decreased significantly over time, yet anti-inflammatory cytokines (IL-4, IL-5, IL-10 and IL-13) decreased to a lesser extent." (PMID 37691941, 2023). "For example, in early infection, S. mansoni eggs induce IL-5 function in recruiting eosinophils to the site of antigen deposition." (PMID 37600806, 2023). "ILC2 exhibited a moderate reduction in intrinsic capacity to produce IL-5 and IL-13 in response to infection; however, when coupled with decreased cellularity, this led to an overall reduction in the number of cytokine-producing ILC2." (PMID 36571761, 2023). "Further, lung CD4+ T cells had significantly increased Th1 (IFNγ) and Th2 (IL-4, IL-5, IL-13) cytokine production potential during patent schistosome infection, at a greater magnitude than observed in pre-patent infection." (PMID 37012228, 2023). "Surprisingly, we found that IL-4, IL-5, IL-6, IL-10, and IL-13 levels reached peaks after 30 days of infection and then decreased in a time-dependent manner." (PMID 37691941, 2023). "As CCL24 was produced by the dermal TRMs themselves, the current studies unveil an additional layer of TRM self-maintenance involving their production of TSLP, which was required to maintain the number of IL-5+ ILC2s in the site of infection." (PMID 38030609, 2023). "Lung CD4+ T cells displayed significantly increased Th1 (IFNγ) and Th2 (IL-4, IL-5, IL-13) cytokine production potential during pre-patent infection at the higher dose." (PMID 37012228, 2023). "Pneumocystis induces a mixed T cell response, so for this study we assessed IFN-γ (type I) and IL-5 (type 2) Elispot responses at 2 weeks after inoculation, a time of peak T cell priming in the lung during infection." (PMID 35917185, 2022). "Similar to the IL-5 KO mice, dblGATA mice showed a higher worm and MF burden with an earlier onset of microfilaremia and prolonged maintenance of the infection compared to wild type controls." (PMID 36389745, 2022). "As a conclusion, the infection of Il-4rα-/-/Il-5-/- mice highlights the subtle balance necessary to control infections while maintaining tissue homeostasis." (PMID 36353644, 2022). "BALF samples collected 4 hours after infection showed higher IL-5, MCP-1, and MIP-1β concentrations in WT as compared with Trpm5–/– mice." (PMID 35503420, 2022). "The Th1 response (IFN-γ and IL-12) in the intestines appeared more persistent until the end of the experiment, while Th2 cytokine (IL-5) expression fold change peaked at 7 dpi and then decreased toward late infection at 28 dpi." (PMID 36187827, 2022). "During extracellular pathogen infection, naïve Th cells proliferate and differentiate toward the Th2 subtype, which functions through secreting various effector cytokines, including IL-4, IL-5, IL-6, IL-10, IL-13." (PMID 35241075, 2022). "L3, IL-5 and eosinophils accumulated in the skin and incoming L3 larvae were eliminated within the first 2 days post infection." (PMID 36389745, 2022). "Type 2 immunity characterized by increased production of the cytokines IL-4, IL-5, and IL-13 contributes to fibrosis following infection with helminth parasites including filariae." (PMID 36353644, 2022). "The level of IL-5 stimulation occurs 5 days after infection when the parasite is thought to be in the luminal phase." (PMID 35646178, 2022). "Direct evidence for the importance of eosinophils in mediating protection against filariae was demonstrated in studies using infections in dblGATA mice, which have IL-5 signaling but lack eosinophils." (PMID 36389745, 2022). "According to a previous study published in 1997, the authors found that IFN-γ, IL-2, IL-3, IL-4, and IL-5 were significantly changed in BALB/c mice after infection with a small amount of H. nana (100 eggs/mouse) at 14 days." (PMID 35878385, 2022). "Consistent with previous studies, Il-4rα-/-/Il-5-/- mice had a higher worm burden in the pleural cavity in the patent phase of infection (70 dpi)." (PMID 36353644, 2022).
infection (continued). "Previous studies have shown that mice that develop persistent bacteriuria have higher levels of the proinflammatory cytokines IL-5, IL-6, KC, and G-CSF in serum at 24 hpi compared to those that ultimately clear the infection." (PMID 35782131, 2022). "The increase in ILC2 numbers in the thoracic cavity of C57BL/6 mice was further accompanied by a strong type 2 immune response characterized by high IL-5 levels at the site of infection." (PMID 35757689, 2022). "In this study, we found that IL-4 and IL-5 still had basic expression levels after 20 days of infection." (PMID 35878385, 2022). "Accordingly, IL-5 transgenic mice, which overexpress IL-5, exhibited enhanced macrophage and eosinophil attachment to the larvae as early as 10 days post infection." (PMID 36389745, 2022). "Until the 10th day after infection, IL-4 and IL-5 were slightly recovered after hitting the low point." (PMID 35878385, 2022). "A mixed Th1/Th2 immune response (overexpressed IFN-γ, IL-12, IL-2, IL-4, and IL-5) was activated as the infection progressed from 7 to 28 dpi." (PMID 36187827, 2022). "Consistent with changes in the T cell response, Il5 and Il13 gene expression in unfractionated duodenal tissue increased upon infection but was curtailed by IL-10R1 blockade, becoming similar to levels seen in naïve mice." (PMID 35428872, 2022). "Cytokines transcriptional trends revealed an immunosuppressive response during early infection stages, with decreased expression of some cytokines, such as IL-12, IL-4, IL-5, IL-1, IL-18, and IL-15, at 2 dpi, 4 dpi, or both compared to control." (PMID 36187827, 2022). "IL-5 upregulation peaked at 7 dpi and then decreased toward late infection at 28 dpi, from 30 to 2.7 times the control." (PMID 36187827, 2022). "Conversely, anti-inflammatory cytokines, such as IL-4, IL-5, IL-10 and IL-13, among others, seem to act to regulate the Th1-type response and favoring the development of infection." (PMID 35891310, 2022). "Considering that only splenic cells derived from mice infected with C. parapsilosis produced IL-10 and IL-5, in addition to pro-inflammatory cytokines, three days post-infection, we analyzed if this distinct scenario persisted during EAE progression." (PMID 35448617, 2022). "All tissues showed increased production of IL-4, IL-5 and IL-13 from wk 6, which either peaked at 8-12 wks post infection or remained elevated into chronic stages." (PMID 35958580, 2022). "Other cytokines (IL-5, IL-1, IL-6, and IL-18) were significantly higher in the intestine at early infection but became higher in the spleen as the infection progressed." (PMID 36187827, 2022). "As expected, CD4+ T cells robustly upregulated type 2 cytokines IL-4, IL-5 and IL-13 by day 7 post-infection." (PMID 34237106, 2021). "But, IL-5, which is traditionally produced in response to IL-4 stimulation, is significantly reduced 48-h post infection, and remains low throughout the course of infection." (PMID 34475490, 2021). "The PLS analysis showed that levels of ITAC, IL-5, IL-7, IL-8, and MIP-1α were associated with pre-infection." (PMID 33731158, 2021). "Though we have yet to examine a role for IL-33 in the neonatal immune response to infection, we have detected both IL-13 and IL-5 within the BALF of P. murina infected BALB/c neonates." (PMID 34682248, 2021). "A previous study showed that phosphorylated STAT5 (p-STAT5) was a key downstream molecule of the PD-1 signaling pathway in ILC2s and inhibited IL-5 and IL-13 expression in the context of infection with Nippostrongylus brasiliensis." (PMID 34194433, 2021). "2-4 weeks post infection with 40 cercariae, S. mansoni antigen stimulated splenocytes show increased expression of IFNγ, as well as the Th2 cytokines IL-5 and IL-4, when compared to uninfected controls." (PMID 33953712, 2021).